NAA40 (N-alpha-acetyltransferase 40, NatD catalytic subunit)
Diseases named in the same sentence as NAA40 in open-access papers (continued):
Sharing a sentence is not in itself a finding about the gene and the disease.
cancer (continued). "The collective data highlight the importance of investigating the role of Naa40 in different cancer tissues." (PMID 26666750, 2016). "Therefore, the Rb/E2F1 axis is likely involved in the transcriptional induction of NAA40 in normal proliferating and cancer cells." (PMID 38864963, 2025). "Furthermore, since NAA40 is consistently found to be upregulated in cancer samples we sought to assess the relative levels of Nt-acH2A.XK5ac in cancerous compared to non-cancerous cell lines." (PMID 40665417, 2025). "Finally, the strong correlation between H2A.X and NAA40 was also replicated in the independent dataset (Cancer Cell line Encyclopedia [CCLE]) of > 1000 cancer cell lines." (PMID 40665417, 2025). "Notably, this analysis highlights a highly consistent transcript landscape for the human NAA40 gene across diverse tissue types, which is also largely unaffected in cancer cells." (PMID 39334865, 2024). "Recent studies have illustrated the essential oncogenic role of NAA40 in various cancer types but its role in chemoresistance remains unclear." (PMID 34785778, 2022). "Moreover, NAA40 was shown to be deregulated and potentially be involved in a greater diversity of human cancers than recognised so far." (PMID 32942614, 2020). "Based on these properties, NAA40 is a potentially druggable enzyme that could be exploited in anti-cancer therapy." (PMID 32680559, 2020). "Several observations support the possibility that reversing aberrant H4/H2A Nt- acetylation in cancer by targeting NAA40 may be an attractive therapeutic strategy." (PMID 32680559, 2020). "Interestingly, immunofluorescence Ki67 staining revealed a significant decrease in the fraction of proliferating cancer cells upon NAA40 depletion." (PMID 30858358, 2019). "We show that NAA40 oncogenic properties stimulate the global levels of H4R3me2s by transcriptionally activating PRMT5 methyltransferase which in turn modulates the expression of key downstream cancer-related genes." (PMID 30858358, 2019). "To investigate whether cgDNA-dependent Naa40 suppression is associated with cell phenotype, we conducted cell viability assays with stable cells since Naa40 is known to be related to apoptosis in cancer cells." (PMID 29867148, 2018). "Epigenetic therapies for cancer treatment hold great promise and future efforts may add Naa40 to the repertoire of epigenetic regulators that are currently being targeted by small-molecule inhibitors in preclinical and clinical studies." (PMID 26666750, 2016). "In the present study, we examine the role of Naa40 in cancer cell survival." (PMID 26666750, 2016). "In sum, the human NAA40 gene encodes two enzymatically active isoforms with distinct biochemical and cellular properties, which potentially perform non-redundant functions in normal and cancer settings." (PMID 39334865, 2024). "Moreover, enriched gene signatures in samples showing high NAA40 expression were also ones indicative of worse prognosis (e.g. WOO_Liver_Cancer_Recurrence_DN; Hoshida_Liver_cancer_Survival_DN; LEE_Liver_Cancer_Survival_UP) consistent with previous observations." (PMID 34150665, 2021). "Similarly to other NATs, Naa40 has emerged through this study as a potential therapeutic target because its inhibition could induce apoptosis in cancer cells and hence hinder carcinogenesis." (PMID 26666750, 2016). "Moreover, we provide evidence showing that NAA40 depletion and loss of N-acH4 significantly reduce the global levels of the adjacent histone mark H4R3me2s through transcriptional repression of PRMT5 which in turn alters the expression of its own cancer-associated target genes." (PMID 30858358, 2019). "Specifically, it was reported that lack of NAA40 and of its associated N-acH4 suppress PRMT5 expression and hence reduce the global levels of H4R3me2s resulting in altered expression of critical cancer-associated genes and the inhibition of CRC cell growth." (PMID 32680559, 2020).
cancer (continued). "In 10 out of the 20 studies, NAA40 mRNA levels were greater than 1.5-fold in this specific cancer tissue, while it was not downregulated in any of them." (PMID 32942614, 2020). "The observation that NAA40 is upregulated in several but not all tumour types, and that it is essential to a subset of all cancer cells, indicate that its oncogenic functions are complex, and vary according to the genetic and/or epigenetic background." (PMID 32942614, 2020). "Additionally, no detrimental effects of targeting NAA40 were observed in non-cancer mouse embryonic fibroblasts, thus it is possible that inhibiting this histone modifier will not affect adversely normal cells." (PMID 32680559, 2020). "Moreover, the link of Naa40 knockdown to apoptosis appears to be specific to cancer cells since depletion of Naa40 in non-malignant embryonic fibroblasts does not stimulate cell death." (PMID 26666750, 2016). "Finally, NAA30 and NAA40 were essential to some, but not all, cancer cells, indicating that their targeting could be particularly effective in specific genetic or transcriptomic contexts." (PMID 32942614, 2020).
tumour (10 papers, 2016 to 2025). "In humans, NAA40 deregulation and the resulting alterations in chromatin architecture are associated with various tumor diseases, positioning NAA40 as a promising therapeutic target." (PMID 36430970, 2022). "In a previous publication examining the NAT family across the TCGA cohort we had reported that the NAA40 mRNA is increased in multiple tumour types, with the most prominent upregulation and association with survival occurring for LIHC patients." (PMID 34150665, 2021). "Specifically, NAA40 stimulates transcription of the one-carbon metabolic gene thymidylate synthase (TYMS), whose product is targeted by 5-fluorouracil (5-FU) and accordingly in primary CRC tumours NAA40 expression associates with TYMS levels and poorer 5-FU response." (PMID 34785778, 2022). "Moreover, it was also shown that NAA40 expression is correlated with loss of hepatic differentiation, more proliferative and aggressive tumours, and a worse prognosis." (PMID 34150665, 2021). "The effects of NAA40 deficiency on CRC cell proliferation in vitro prompted us to examine whether NAA40 regulates CRC tumor growth in vivo." (PMID 30858358, 2019). "To verify the upregulation of NAA40 in normal vs. tumour liver tissue, we also examined 20 studies deposited in the GEO omnibus." (PMID 32942614, 2020). "In both the developing liver in vivo and in the differentiating ES models, the levels of NAA40 were gradually decreasing, indicating that NAA40 is developmentally repressed in the liver lineage, but reactivated in tumour tissue." (PMID 32942614, 2020). "In agreement to effects observed with tumor volume, the weight of resected tumors from dox-treated NAA40-KD mice was reduced to ~33% of the weight in the control groups." (PMID 30858358, 2019). "In addition to the delayed tumour growth, NAA40 overexpressing explants in mice treated with 5-FU showed increased tumour weight and size compared to the empty vector tumours in the equivalent treatment group." (PMID 34785778, 2022). "This may suggest that NAA40 upregulation occurs from the initial stages of malignant progression and is sustained along the different tumor stages." (PMID 30858358, 2019). "Therefore, we wanted to ascertain whether this tumour suppressor plays a role in the induction of apoptosis once Naa40 is depleted." (PMID 26666750, 2016). "Further investigations into the genes and pathways regulated by NAA40 in LIHC and the potential consequences of targeting this enzyme for tumour growth and survival are therefore warranted." (PMID 34150665, 2021). "In this study, we show that NAA40 is significantly upregulated in primary CRC tissues and promotes CRC cell growth both in vitro and in xenograft tumor models." (PMID 30858358, 2019). "Consistent with the observations above, the expression of NAA40 was significantly lower in samples classified in iCluster 2, which are less aggressive tumours and belong in the non-proliferation class." (PMID 34150665, 2021). "Additionally, our findings illustrate that conditional depletion of NAA40 blocks the growth of multiple CRC cell lines and inhibits xenograft tumor formation in mice." (PMID 30858358, 2019). "Furthermore, similarly to NAA40, PRMT5 expression levels are also increased in all tumor stages in CRC patients." (PMID 30858358, 2019). "However, compared to adjacent normal liver, a significant upregulation of NAA40 transcript was observed in all tumour samples regardless of the infecting agent, consistent with the general upregulation of NAA40 in LIHC." (PMID 34150665, 2021).
NAA40 also shares sentences with these, for which no sentence is quoted: liver disease (1 paper); myelocytic leukemia (1).